KRAS (KRas proto-oncogene, GTPase)
Diseases named in the same sentence as KRAS in open-access papers (continued):
Sharing a sentence is not in itself a finding about the gene and the disease.
prostate carcinoma (114 papers, 2005 to 2026). A carcinoma that arises from epithelial cells of the prostate gland. "Prior work demonstrates KRAS or MAPK activation is linked with prostate cancer aggressiveness, and this is explained in part by EZH2-mediated suppression of the negative regulator of Ras59,60." (PMID 40624104, 2025). "FBXW2 is considered a powerful therapeutic target for many other solid tumors, such as lung, breast, and prostate cancers, most of which display frequent KRAS mutations." (PMID 40721413, 2025). "It is assumed that heterozygous loss of KRAS in patients having prostatic cancer with fewer than ten CTCs had a clear reduction rate of mutations." (PMID 40026568, 2024). "For example, single-cell KRAS sequencing of CTCs in patients with prostate cancer using NanoVelcro/LCM platform noted that CTCs count was associated with the presence of KRAS mutations." (PMID 40026568, 2024). "Mutations in KRAS account for 7% of prostate cancer cases and have been linked to effector proteins such as RAF, PI3K and GDP/GTP Ral exchange factor, contributing to downstream signaling responses." (PMID 33801965, 2021). "A lower efficiency of antibody 9F7-F11 on pERK1/2 was observed in DU145 cells, probably due to the fact that this prostate cancer cell line exhibits KRAS mutation G12V." (PMID 27203743, 2016). "The mutation frequency of KRAS ranged from 3 to 16% in the Asian population, but was below 4% in western patients with prostate cancer." (PMID 25004126, 2014). "Most importantly, our findings will contribute to a better understanding to further justify the clinical use of EGFR inhibitors in patients with KRAS mutation in prostate cancer." (PMID 25004126, 2014). "For the KRAS gene, the frequency of mutation in relation to prostate cancer has been reported across a range of geographical regions, races and patient cohorts." (PMID 25004126, 2014). "In order to assess whether down-regulation of miR-203 is necessary for cellular transformation induced by oncogenic KRAS expression, we analyzed the functional effects of miR-203 on cell invasion and growth in Ras-mutated prostate cancer cells." (PMID 25004126, 2014). "However, it has been reported that the frequency of KRAS mutations in prostate cancer patients from East Asian countries was much higher than that in American cases." (PMID 23852643, 2013). "A pan-KRAS inhibitor effectively suppressed AR-independent prostate cancer cells by disrupting KRAS-mediated cell survival signaling." (PMID 42069672, 2026). "Our research demonstrated that KRAS has minimal influence during the AR-dependent stages of prostate cancer but significantly activates cancer cells when AR signaling is suppressed." (PMID 42069672, 2026). "Further, the gene set enrichment analysis (GSEA) of RNA sequencing data shows that genes of several pathways critical for prostate cancer progression including DNA replication, sister chromatid segregation and KRAS signaling are downregulated by VNPP433-3β." (PMID 36831540, 2023). "Previous studies in prostate cancer have also shown that miR-143-3p can inhibit cell growth through various targets, including KRAS, Bcl-2, ERK5, LIMK1, HK2 and KLK2." (PMID 37759434, 2023). "For example, in studies on the tumor microenvironment, exosomes secreted from KRAS‐mutant prostate cancer cell lines have been found to contain small RNAs and to induce aggressive tumors in secondary recipients." (PMID 36718590, 2023). "MAZ promotes bone metastasis of prostate cancer through transcriptional promotion of the KRas/RalGEFs signal path." (PMID 36890610, 2023). "The differences in the KRAS.PROSTATE_UP.V1_DN. gene set suggest that the changes of genes in the hippocampus of AD patients are similar to those of epithelial prostate cancer cell lines." (PMID 35637434, 2022).
prostate carcinoma (continued). "Paradoxically, deficiency or silencing of MFF also induced apoptosis in cardiomyocytes, HeLa, prostate cancer and KRAS-transformed salivary duct cancer cells." (PMID 34745083, 2021). "Mutant KRAS is known to be a transformative factor in prostate cancer and found to promote cancer stemness and bone metastasis." (PMID 33801965, 2021). "In serum, CNV in CCND1 was associated with MVI (p = 0.004); CNV in PTP4A, KRAS, ERBB2, TOP2A with positive STSM (p ≤ 0.035); CNV in CCND1 with the presence of incidental prostate cancer (p = 0.018)." (PMID 33298978, 2020). "There was an inverse correlation between expressions of miRNA-143 and KRAS protein in prostate cancer samples." (PMID 30744689, 2019). "Theoretically, KRas mutation in this site will block the transcriptional activation of KRas by MAZ and thus affect the occurrence of bone metastasis of prostate cancer." (PMID 31488180, 2019). "PseudoFuN query of KRAS identified co-expression patterns in prostate cancer consistent with ceRNA network regulation by hsa-miR-145, a known modulator of KRAS in prostate cancer." (PMID 31029062, 2019). "Particularly, they have explored the functional synergy in prostate cancers in mice resulting from the activation of the AR, KRAS, and AKT." (PMID 31366128, 2019). "KRAS is well-recognized as a transformative factor in prostate cancer and gene amplification at KRAS loci (e.g. increased copy number) has also been detected in many tumors including prostate." (PMID 31009485, 2019). "A software pipeline, Flexible Algorithm for Novel Gene set Simulation (FANGS) develops simulated data based on a prostate cancer dataset where the KRAS and TGF-β pathways were differentially expressed." (PMID 29881462, 2018). "In prostate cancer, oncogenic KRAS signalling led to suppression of miR-143/145 cluster by activating Ras-responsive element-binding protein 1 (REBB1)." (PMID 29360852, 2018). "While miRNA deregulation has been associated with aberrant expression of BCL2, KRAS and PTEN in other type of cancers, further studies are needed to shed light on their role in prostate cancer." (PMID 29268752, 2017). "An analysis of mean expression confirmed that miR-34a was highly expressed in tissues of primary and metastatic stage prostate cancer with down-regulated KRAS signatures." (PMID 25436980, 2015). "Taken together, it appears that miR-203 regulates anti-apoptotic proteins as well as an oncogenic molecule and acts independently as a tumor suppressor by regulating additional targets in KRAS-activated prostate cancer cells." (PMID 25004126, 2014). "A recent study has shown that miR-143 plays an important role in prostate cancer proliferation, migration and chemosensitivity by suppressing KRAS." (PMID 23383988, 2013). "Additionally, CCL2, secreted by AR-inhibited prostate cancer cells, induces FGF8b secretion from stromal cells within the tumor microenvironment, which in turn enhances KRAS activation." (PMID 42069672, 2026). "This study suggests that naringenin (NAR) and oleuropein (OLE) may exert antiproliferative and regulatory effects in prostate cancer cells, and that this may be regulated by modulating miR-155-5p-mediated KRAS/CDK2 targets." (PMID 41595499, 2026). "In addition, KRAS has been implicated in regulating the expression of Gli proteins in the KRAS-androgen axis in prostate cancer." (PMID 38481800, 2024). "Finally, miR-143 has been shown to decrease proliferation and migratory aptitude of prostate cancer cells while enhancing the cytotoxic effects of docetaxel via inhibiting KRAS." (PMID 35139853, 2022). "Future clinical trials will confirm whether targeting MEK/ERK in KRAS mutant cancers will be effective in the treatment of prostate cancer." (PMID 33801965, 2021).
prostate carcinoma (continued). "In prostate cancer, KRAS regulates ILK expression mediated by E2F1 in a KRAS-E2F1-ILK-hnRNP1 loop." (PMID 34233735, 2021). "In addition, KRAS rearrangements have been shown to promote the metastatic progression of prostate cancer." (PMID 33801965, 2021). "DE genes were enriched in the signature of the KRAS-dependent Prostate Cancer in both directions." (PMID 34183044, 2021). "MiRNA-30 c could suppress prostate cancer survival by targeting KRAS Proto-Oncogene, E2F Transcription Factor 7 (E2F7), or alternative splicing factor/splicing factor 2 (ASF/SF2)." (PMID 34503377, 2021). "In addition, MAZ plays a key role in promotion of prostate cancer bone metastasis via transcriptional activation of the KRas/RalGEFs pathway." (PMID 34183010, 2021). "In addition, KRAS and androgen receptor synergistically simulate tumor-propagating cells in prostate cancer." (PMID 32101536, 2020). "KRAS amplifications has been reported in various malignancies, primarily in pancreatic, colorectal and lung tumors, but also have been noted in gastric, ovarian and endometrial malignancies, but less frequently in prostate cancers." (PMID 31009485, 2019). "MiRNA-143 could also inhibit the proliferation and migration of prostate cancer cells, which were mediated by the downregulation of Kirsten rat sarcoma viral oncogene (KRAS)." (PMID 30744689, 2019). "The AR negative tumor PC_6864 carried a KRAS p.G12R mutation that is known to cause constitutive KRAS activation in cancers of the colon, pancreas and lungs, but is less common in prostate cancer." (PMID 25749039, 2015). "In order to assess whether the down-regulation of miR-34a is necessary for KRAS-induced cellular transformation, we analyzed the functional effects of miR-34a on cell growth and invasion in Ras-activated prostate cancer cells." (PMID 25436980, 2015). "Moreover, we observed a high expression of AREG, EREG, and TGFA in tumors that had higher KRAS oncogenic response gene signatures in the human prostate cancer dataset." (PMID 25004126, 2014). "NSCLC, for instance, frequently involves KRAS mutations and EGFR pathway alterations, which may interact differently with statin-induced modulation of signalling pathways compared to prostate cancer, where androgen receptor signalling and lipid metabolism are more prominent." (PMID 41163198, 2025). "KRAS has been characterized as a cancer-related gene with potential importance for future cancer treatment, while RAD51 and XRCC3 polymorphisms may be associated with an increased risk of prostate cancer." (PMID 33240468, 2020). "Interestingly, any of these two events was sufficient to promote the formation of prostate cancer, but only the functional synergy of the oncogenic function of AR and KRAS signaling could promote prostate cancer progenitors in vivo and elevate EZH2 expression." (PMID 31366128, 2019). "miR-143 could increase the drug-sensitivity of prostate cancer by suppressing the expression of target protein KRAS, while the overexpression of miR-143 could also participate the regulation of EGFR/RAS/MAPK pathway and improve the sensitivity of prostate cancer cells to docetaxel." (PMID 25342041, 2014). "In prostate cancer, MAZ promotes bone metastasis through transcriptionally activating the KRas‐dependent RalGEFs pathway, and MAZ binds to the CDH1 promoter to promote epithelial‐mesenchymal transition (EMT)." (PMID 40411278, 2025). "Our finding of reduced miR-143-3p in prostate cancer tissue relative to BPH is consistent with those reports and reinforces the idea that loss of miR-143 may contribute to prostate tumorigenesis by unleashing pro-proliferative pathways such as the KRAS signaling pathway." (PMID 41462933, 2025). "We performed a dose–response study using previously designed PPRHs against KRAS and MYC in the prostate cancer cell line PC-3." (PMID 39457457, 2024).
prostate carcinoma (continued). "In this work we focused on our understanding of the cooperative dynamics between these oncogenes, by investigating the combined impact of PPRHs targeting KRAS and MYC in pancreatic and prostate cancer cells." (PMID 39457457, 2024). "Synergistic cancer cell killing by the combination of olaparib and PLK1 inhibition, using other small molecules, including BI2536 and BI6727 (volasertib), has been reported in castration-resistant prostate cancer and in HGOC cells with KRAS amplification." (PMID 39039067, 2024). "In prostate cancer, upregulated-MAZ promotes bone metastasis through the transcriptional activation of the KRas-dependent RalGEFs pathway." (PMID 34183010, 2021). "We have previously reported that ERG can mimic KRAS in prostate cancer cells, whereby both ERG and KRAS activate a similar gene expression program that promotes cell migration." (PMID 33554122, 2021). "Oncogene KRAS is a key molecule of EGFR/RAS/MAPK pathway, and miR-143 can restore chemosensitivity to docetaxel in prostate cancer cells by down-regulating KRAS." (PMID 24106980, 2013). "While the prognostic value of HDGF has not yet been evaluated before, previous studies have shown that downregulation of HDGF inhibited migration and invasion of prostate cancer cells, and HDGF activated the MAPK/ERK pathway via KRAS and RhoA mediation in cell line models of prostate cancer." (PMID 39402324, 2024). "They reported that mutant KRAS was detected in CTCs isolated from prostatic cancer (92 %) with more than ten CTCs count whereas none of the other hematopoietic cells analyzed from the same patient had shown any such mutations." (PMID 40026568, 2024). "Similar to what has been described for blood cancers, there are no therapies directly targeting KRAS in prostate cancer, but other proteins upstream and downstream of KRAS have attracted interest as potential targets." (PMID 33801965, 2021). "Moreover, in prostate cancer, EZH2 can repress the expression of tumor suppressors such as DAB2IP, p16 (CDKN2A), CDK4, E-cadherin (CDH1), MSMB, Ras (KRAS), NF-κB (NFKB1), EMT regulator." (PMID 27835578, 2016). "This indicats that tissues from non-tumor prostate tissues, primary and metastatic stage prostate cancer tissues dataset, with down-regulated KRAS signatures, have more TCF7 and BIRC5 expression." (PMID 25436980, 2015). "DU145 cells, which have a KRAS gene rearrangement, did not have high levels of any oncogenic ETS protein, or pAKT, but did have pERK, consistent with the small fraction of prostate cancers with RAS/ERK pathway mutations." (PMID 24642271, 2014). "Although constitutive activation of RAS-RAF-MAPK pathway occurs in a majority of advanced prostate tumors, the incidence of direct mutations of the upstream activators such as KRAS and BRAF are not commonly found in prostate cancer." (PMID 23852643, 2013). "PC-3 cells in the prostate cancer dataset GSE179990 showed greater overall enrichment in samples expressing the shorter isoform (318 bp long) of NF-YA, than its longer isoform (347 bp long), with the top signature being ‘KRAS.600_UP.V1_UP’ (NES = 2.049, p-value < 0.001)." (PMID 39857756, 2025). "Another study identified the oncogenic UBE2L3-KRAS fusion in DU145 prostate cancer cells using an integrative genomics approach, and further investigation demonstrated that the fusion of UBE2L3 with KRAS may lead to the progression of metastases in rare subsets of prostate cancer." (PMID 35265070, 2022).
leukemia (108 papers, 2009 to 2026). A malignant (clonal) hematologic disorder, involving hematopoietic stem cells and characterized by the presence of primitive or atypical myeloid or lymphoid cells in the bone marrow and the blood. "Concurrent therapies consisted of dasatinib for a Ph-positive ALL, venetoclax for another, and trametinib for a patient with KRAS-mutated leukemia." (PMID 40110204, 2025). "These NS-associated mutations are distinct from those seen in cancers and leukemias; for instance, the KRAS T58I allele (found in NS) has milder effects compared to the classic oncogenic KRAS G12D mutation or wild-type KRAS." (PMID 39682300, 2024). "KRAS mutations have recently been described as an independent adverse prognostic factor in pediatric KMT2Ar AML by the Japanese Pediatric Leukemia/Lymphoma Study Group, which was validated using a smaller cohort of adult KMT2Ar patients." (PMID 38965370, 2024). "Oncogenic KRAS in leukemia was shown to cause the activation of the NLRP3 inflammasome, which appeared to take on a key role in the development of cytopenia, splenomegaly and myeloproliferation." (PMID 35965494, 2022). "Although TBK1 mutations have not been reported in human cancers, aberrant TBK1 activation has been implicated in the oncogenesis of several types of cancer, including leukemia and solid tumors with KRAS-activating mutations." (PMID 35395857, 2022). "Despite the high KRAS mutation rate in various leukemias and myeloma cases, the development of therapeutics specifically targeting KRAS has been a challenge." (PMID 33801965, 2021). "The expression of KRAS4A in KRAS-mutated leukemia cell lines and acute myeloid leukemia (AML) cells were checked using western blotting and reverse transcriptions-quantitative polymerase chain reaction (RT-qPCR) analysis, respectively." (PMID 26715448, 2015). "We show here that KRAS4A is expressed in human leukemia cell lines and in AML cells harboring KRAS mutations and that mutation at the palmitoylation site of oncogenic KRAS4A significantly abrogates its leukemogenic potential." (PMID 26715448, 2015). "Here, we generated a fly leukaemia model induced by expressing one human KRAS mutation." (PMID 34797366, 2022). "Therefore, understanding the role of KRAS mutations in large-scale alterations in the transcriptional profiles of leukemia cells, including the dysregulation of lncRNA expression, provides more details on the pathogenic mechanisms." (PMID 34489556, 2022). "It is not clear whether HRAS mutations outside these hotspots are non-functional passenger mutations or rare activating mutations which have been identified e.g. for N- and KRAS in leukemia." (PMID 26544513, 2015). "MM harbors both oncogenic activating mutations of KRAS and NRAS 1, and while ALL and AML also harbor KRAS A146 mutations, these leukemias preferentially express mutant forms of NRAS44." (PMID 41542462, 2026). "In summary, this study suggests that PROTAC-mediated SOS1 degradation represents an effective therapeutic strategy for treating not only KRAS-mutant cancers but also BCR–ABL–harboring leukemia." (PMID 39437162, 2025). "We recommend further studies to investigate if the risk of developing leukemia after RAI treatment is heightened in the presence of any specific mutations, such as BRAF or KRAS." (PMID 39796657, 2024). "KRAS knockout is embryonically lethal and KRASG12D knockin mutation caused CD4+/CD8+ double positive T lymphoblasts leukemia in the mice model." (PMID 38898200, 2024). "Common mutations found in leukemia patients, such as ABL1, FGFR1, KRAS, MET, NOTCH1, and PTPN11, were also found among our patient population, although not universally." (PMID 37092520, 2023).